AQP4 (aquaporin 4)
Diseases named in the same sentence as AQP4 in open-access papers (continued):
Sharing a sentence is not in itself a finding about the gene and the disease.
ischemic stroke (continued). "Although our study has shed light on several aspects of the role of AQP4 after ischemic stroke, it is crucial to acknowledge the potential limitations and confounders." (PMID 39444081, 2024). "Previous in vitro studies about the edema that occurs during the early stage of ischemic stroke and brain trauma show the role of AQP4." (PMID 37569597, 2023). "Although far from being completely understood, the finding suggested that TMP induces the transformation of astrocytes into the neuroprotective A2 subtype at least in part, via regulating AQP4 and Cx43 after ischemic stroke." (PMID 37051111, 2023). "In several ischemic stroke models, AQP4 contributes to brain edema formation, and its absence disables cellular water uptake." (PMID 37840921, 2023). "This reveals that AQP4 plays an important role in astrocyte injury after ischemic stroke, and inhibition of miR-145 expression can increase cerebral edema and worsen the prognosis due to increased expression of AQP4." (PMID 35755778, 2022). "When AQP4 is knocked-out or inhibited, formation of cerebral edema after ischemic stroke is reduced." (PMID 36061592, 2022). "A modified phenylbenzamide compound (AER-270) inhibited AQP4 function in vitro and reduced cerebral edema in models of ischemic stroke." (PMID 35145418, 2022). "Deciphering changes in AQP4 are helpful to understand its roles in the pathology of ischemic stroke; however, most analytical methods remain highly invasive or destructive." (PMID 35592320, 2022). "Several studies have shown that the up-regulation of AQP4 following ischemic stroke increases cytotoxic edema at early stage, but other studies reported downregulation, which is consistent with our study." (PMID 36582539, 2022). "Previous studies reported that the level of AQP4 was higher in patients who showed neurological improvement after the onset of ischemic stroke." (PMID 35711733, 2022). "The perivascular astrocytes polarize in SCI, ischemic stroke, and tumors to upregulate the expression of AQP4 on cell membranes, resulting in end-foot edema and vascular regression." (PMID 36710937, 2022). "Research has proposed that increasing ALDH2 activity can improve ischemic stroke in rats via inactivation of AQP4 expression." (PMID 34362382, 2021). "Emerging evidence supports the notion that increasing ALDH2 activity can improve ischemic stroke in rats by downregulating aquaporin 4 (AQP4) expression." (PMID 34362382, 2021). "It was notably that AQP4-knockout inhibited edema and improved neurological outcome in the ischemic stroke or acute water intoxication model, which seems to be contradictory to results in SAH or ICH described here." (PMID 34975411, 2021). "In this area, we are aware of only one study that analyzed the levels of AQP4 in the circulation in neurological disorders, reporting higher levels of AQP4 in ischemic stroke patients after the acute phase of the disease." (PMID 33801197, 2021). "In a rodent model of ischemic stroke, ET-1 overexpression results in upregulation of AQP4 at astrocyte endfeet." (PMID 34082828, 2021). "In the ischemic stroke mouse model, the presence of AQP4 was shown to aggravate post-ischemic cytotoxic edema as measured by post-ischemic hemispheric enlargement, while AQP4-null mice showed an opposite effect with an improved neurological outcome." (PMID 33796134, 2021). "This has important implications for cytotoxic oedema formation and dissolution, as perivascular AQP4 allows bidirectional water flow, and therefore is most likely to be the rate-limiting step for both water influx and efflux after ischaemic stroke." (PMID 33924191, 2021). "Overexpression of AQP4 induces brain edema, whereas AQP4 deletion reduces brain edema after acute water intoxication and ischemic stroke." (PMID 33133067, 2020). "Aquaporin 4 (AQP4) is a key factor mediating the cell swelling and edema that occurs during ischemic stroke, and plays a potential role in the migration and proliferation of GBM tumor cells." (PMID 31019448, 2019).
ischemic stroke (continued). "Overexpression of AQP4 is detrimental to survival after water intoxication, and AQP4 deletion improves survival after water intoxication as well as ischemic stroke." (PMID 31187032, 2019). "As a crucial functional marker of astrocytes, AQP4 is responsible for water transport, and it plays an important role in progression and recovery following ischemic stroke (notably as part of brain edema and likely in the clearance of toxic metabolites)." (PMID 31382635, 2019). "AQP4 played an essential part in the formation and dissipation of cerebral edema in the early ischemic stroke." (PMID 30233364, 2018). "In vivo and in vitro experiments on ischemic stroke have reported that specific signal transduction pathways regulate AQP4 expression." (PMID 29057271, 2017). "After confirming the histopathology of ischemic stroke with minimal hemorrhagic transformations (see Supplementary Results), we have first sought to evaluate the expression of AQP4 in these animals." (PMID 29295526, 2017). "Together, these results support the potential therapeutic utility of AQP4 in treating brain edema induced by brain injuries including ischemic stroke." (PMID 28503134, 2017). "The mitogen-activated protein kinase (MAPK) pathways play an important role in AQP4 upregulation in ischemic stroke." (PMID 29057271, 2017). "In an ischemic stroke model, the presence of AQP4 was shown to aggravate post-ischemic cytotoxic edema, while AQP4-KO mice demonstrated an improved neurological outcome." (PMID 27242432, 2016). "For example, it has been reported that, after an ischemic stroke, AQP4 accelerates edema development, and AQP4 clearly increases after traumatic brain injury." (PMID 27367682, 2016). "Mesenchymal stem cell therapy can repress inflammation during ischemic stroke in mice, thereby protecting the integrity of the blood-brain barrier, reducing brain edema and astrocyte apoptosis, and downregulating AQP4 expression via the p38 signaling pathway." (PMID 27517922, 2016). "Conversely, cytotoxic edema, which appears during the early stages of ischemic stroke, is correlated with a downregulation of AQP4 channels." (PMID 27438832, 2016). "Altogether, these results suggest that AQP4 upregulation plays a significant role in the formation of vasogenic edema following both hemorrhagic and late ischemic stroke." (PMID 27438832, 2016). "For ischemic stroke, genetic deletion of AQP4 ameliorated brain edema following focal ischemic stroke." (PMID 26089944, 2015). "In the ischemic stroke model, the presence of AQP4 was shown to aggravate post-ischemic cytotoxic edema as measured by post-ischemic hemispheric enlargement, while AQP4-KO mice exhibited an opposing effect and an improved neurological outcome." (PMID 25904843, 2015). "Sanhua decoction (SHD) is a famous classic Chinese herbal prescription for ischemic stroke, and aquaporin 4 (AQP4) is reported to play a key role in ischemic brain edema." (PMID 26089944, 2015). "Heterogeneous AQP4 expression patterns and their alterations in pathological states however add to the complexity of tackling the pathophysiology in ischemic stroke." (PMID 25904843, 2015). "Evidence that AQP4 is responsible for cytotoxic brain edema is indicated by studies of AQP4-null mice, where AQP4 deletion reduced cytotoxic brain edema in water intoxication and ischemic stroke mice." (PMID 25941935, 2015). "The role of AQP4 in ischemia was first described in an AQP4-KO model of combined cytotoxic and vasogenic brain edema (ischemic stroke model) and a cytotoxic brain edema model (acute water intoxication model)." (PMID 25904843, 2015). "The expression of AQP4 is up-regulated in wild type mice and AQP4 null mice have significantly less brain edema in water intoxication cerebral edema, ischemic stroke and pneumococcal meningitis." (PMID 23036239, 2012). "Lately, AQP4 has become a potential therapeutic target to treat cerebral edema during ischemic stroke." (PMID 22438957, 2012).
ischemic stroke (continued). "AQP4 knock-out mice with ischemic stroke and bacterial meningitis showed decreased cerebral edema and improved outcomes." (PMID 21119879, 2010). "The significantly high expression of AQP4 after ischemic stroke may promote the formation of ischemic edema." (PMID 41329542, 2025). "AQP4 might potentially contribute to astrocytic swelling and cytotoxic edema by facilitating water influx into astrocytes during the early stages of ischemic stroke." (PMID 39944892, 2025). "Notably, miR-29b overexpression has been shown to reduce BBB disruption in ischemic stroke by downregulating Aqp4." (PMID 40529227, 2025). "These pro-inflammatory cytokines promote AQP4 transcription by activating the NF-κB signaling pathway.During the pathological process of ischemic stroke, miR-29 is downregulated, leading to increased AQP4 expression, which exacerbates brain edema and BBB disruption." (PMID 41451205, 2025). "AQP4 perivascular expression is reduced at the injury site after ischemic stroke." (PMID 40277075, 2025). "may exert therapeutic effects in ischemic stroke by downregulating AQP4, which in turn inhibits the upregulation of MMP-9 and suppresses the water flux across brain microvascular endothelium to astrocytes." (PMID 41409597, 2025). "In conditions like ischemic stroke, where AQP4 is overexpressed in astrocyte endfeet, the increased opportunity for water entry could be an underlying factor for astrocytic edema." (PMID 38988660, 2024). "Moreover, pyroptosis of astrocytes and microglia is able to trigger the accumulation of amyloid-beta peptide (Aβ) and BBB dysfunction in ischemic stroke by inhibiting the polarization of aquaporin-4 (AQP-4)." (PMID 38026442, 2023). "Recent studies have shown that astrocytes may be involved in the development of edema following ischemic stroke by increasing the expression of AQP4." (PMID 37464832, 2023). "In this study, we demonstrated that astrocytes can damage brain tissue by releasing Glu, enhancing Ca2+ activity, and upregulating AQP4 expression; however, they can also protect brain tissue by their astrocytic syncytium structure formed by gap junctions in the early stage of ischemic stroke." (PMID 37464832, 2023). "The significantly high expression of AQP4 after ischemic stroke may promote the formation of cerebral edema." (PMID 36061592, 2022). "The use of AQP4 inhibitors after ischemic stroke has become a research hotspot." (PMID 36061592, 2022). "In addition, Cav-1 deficiency leads to decreased AQP4 expression and impaired perivascular AQP4 coverage after ischemic stroke." (PMID 35873558, 2022). "In conclusion, we found acutely inhibiting AQP4 with TGN-020 not only decreased the edema at the early stage of ischemic stroke but also reduced peri-infarct astrogliosis and AQP4 depolarization, promoting sensorimotor and cognitive recovery at the subacute stage." (PMID 35592320, 2022). "Further investigation suggested that lncRNA Malat1 could positively regulate the expression of aquaporin-4 (AQP4) by competitively binding miR-145 to mediate the damage of astrocytes during ischemic stroke." (PMID 35346266, 2022). "Interestingly, reduced AQP4 expression and anti-edematous effects have been shown in ischemic stroke rodents following T3 administration." (PMID 36498538, 2022). "The study has found that miR-130b promotes neuroprotection by binding to the 3’UTR region of AQP4 mRNA and downregulating AQP4 levels in astrocytes at the post-transcriptional stage miR-130b may be a novel target for treating ischemic stroke." (PMID 36710937, 2022). "Another relevant pathology is ischemic stroke, where AQP4 is overexpressed at site of infarction; AQP4 blockage could be a new therapeutic strategy to treat this condition." (PMID 33499944, 2021). "Several studies reported the opposite role of AQP4 in the pathology of ischemic stroke." (PMID 34305569, 2021).
ischemic stroke (continued). "Experiments conducted using AQP-4-deficient mice showed that AQP-4 promotes the formation of cytotoxic edema, whereas the absence of AQP-4 reduces edema severity after acute water intoxication, ischemic stroke, and SCI." (PMID 35002629, 2021). "The dual role of AQP4 in ischemic stroke is mainly due to its spatial expression heterogeneity." (PMID 34305569, 2021). "Aquaporin-4 plays a complex bimodal function in the pathology of ischemic stroke." (PMID 34305569, 2021). "Currently, a series of studies reported AQP4 expression after ischemic stroke." (PMID 34305569, 2021). "AQP4 is a major target of vasopressin in ischemic stroke-evoked brain edema injury." (PMID 32985231, 2020). "Moreover, several miRNAs, such as miR-29b and miR-130a, regulate AQP4 expression in ischemic stroke." (PMID 33192260, 2020). "AQP4, which governs water flux, obviously plays an important role in brain edema, as it has been shown that brain edemas induced by water intoxication or ischemic stroke may be reduced in AQP4 null mice." (PMID 30759771, 2019). "Considering the pathophysiological role of AQP4 in a range of CNS disorders including ischemic stroke, neuroinflammation and autoimmune neurodegenerative diseases, the reversal of cerebral oedema induced through AQP4 activity by monoterpenes is an interesting observation." (PMID 29316661, 2018). "Further investigation may be needed to demonstrate the exact pathophysiological roles of GS and AQP4 in the context of ischemic stroke." (PMID 29628876, 2018). "Moreover, AQP4 enhanced astrocyte injury in ischemic stroke, and AQP4 knockdown diminished the miR-145-mediated protective effect on ischemic injury." (PMID 29057271, 2017). "Human brain tissues from control and ischemic stroke cases were immunolabeled for Aqp4 to determine whether white matter and grey matter astrocytes exhibit different patterns of Aqp4 subcellular localization following ischemic stroke." (PMID 26419740, 2015). "However, this animal model is eligible to further study the properties of AQP4 in ischemic stroke in-vivo." (PMID 25986484, 2015). "A potentially viable compound which is postulated to interact with AQP4 and which may be useful in ischemic stroke is edaravone, a free radical scavenger that readily crosses the BBB." (PMID 25904843, 2015). "However, AQP4 plays a complex dual role in the pathology of ischemic stroke." (PMID 39927473, 2025). "Similarly, the classic formula Wuling Powder has been shown in mice to reduce brain water content after ischemic stroke by suppressing AQP4, a mechanism that involves Mn2+ and Zn2+ ions and is consistent with its observed inhibition of AQP4-dependent permeability in MLE-12 cells." (PMID 41451367, 2025). "Furthermore, we detected the expressions of AQP4 and Cx43, astrocytic A1/A2 reactivity, and FGF2/PI3K/AKT pathway to develop in-depth knowledge of the possible repair mechanisms underlying TMP treatment after ischemic stroke." (PMID 37051111, 2023). "Reduction of AQP4 expression and translocation from astrocytic end feet leads to cytotoxic edema, and inhibitors of this translocation could reduce cytotoxic edema and potentially be neuroprotective for ischemic stroke." (PMID 37388676, 2023). "Moreover, we sought to determine whether ischemic stroke-induced brain edema, which is the dysregulated movement of fluid through the water channel aquaporin 4 (AQP4), can be regulated by 2G11 treatment." (PMID 36358564, 2022). "Therefore, AQP4 inhibitors may be a therapeutic option for reducing cytotoxic oedema after ischaemic stroke." (PMID 33924191, 2021). "In summary, the effects of AQP4 on the pathophysiological process of ischemic stroke are very complex, and more studies are needed to further investigate the spatial and temporal differences of AQP4 expression and its role in different phase of ischemic stroke." (PMID 34305569, 2021).
ischemic stroke (continued). "AQP-4, the main component of glymphatic system, is a water channel physiologically located with high polarization on astrocytic endfeet, and the loss of AQP-4 polarization can cause the dysfunction of glymphatic system in pathological changes including AD and ischemic stroke." (PMID 34434229, 2021). "Therefore, we hypothesized that miR-145 may exert its function in ischemic stroke by targeting AQP4." (PMID 29057271, 2017). "Therefore, inhibiting AQP4 channel function may be a potential target for ischemic stroke treatment." (PMID 29057271, 2017). "For instance, AQP4 inhibition could provide new treatments by reducing cytotoxic edema during early ischemia, whereas vasogenic edema that appears in late ischemic stroke or hemorrhagic stroke could be potentially controlled by increased expression of AQP4, AQP4 up-regulators or activators." (PMID 25904843, 2015). "However, there are still reported conflicts regarding the role of AQP4 in ischemic stroke." (PMID 24416250, 2014). "The upregulation of AQP4 is closely related to astrocyte swelling, which subsequently leads to apoptosis of astrocytes and BBB collapse in the early onset of ischemic stroke." (PMID 40360812, 2025). "In ischemic stroke rats, neutrophil-derived IL-1α/TNF induce Aquaporin-4 polarization to perivascular astrocyte end-feet, disrupting water homeostasis." (PMID 40510212, 2025). "Contemporary evidence highlights the dual challenges of acute blood pressure management in ischemic stroke and chronic hypertensive vasculopathy, wherein prolonged hypertension induces BBB disruption through aquaporin-4 (AQP4)-mediated edema formation." (PMID 41394000, 2025). "However, in the later stages of ischemic stroke, when vasogenic edema becomes the primary cause of brain swelling due to the BBB breakdown, AQP4 could serve the purpose of alleviating brain edema by mediating the transport of excess water from the interstitial space to the GS." (PMID 39944892, 2025). "Our findings illustrated AQP4 and Cx43 in TMP-mediated astrocytes following ischemic stroke, which brought new clues for exploring the mechanism of TMP-induced NVU protection and endogenous neurovascular remodeling." (PMID 37051111, 2023). "Furthermore, we revealed that AQP4 polarization correlated negatively with astrogliosis in the peri-infarct area, indicating therapies targeting astrogliosis might be effective to preserve AQP4 polarization and promote neurological recovery in ischemic stroke." (PMID 35592320, 2022). "Even though TGN-020 shows promising results after ischemic stroke and spinal cord injury, TGN-020 also has an affinity to AQP1, which is similar to AQP4, with about 60% homology." (PMID 34502395, 2021). "In ischemic stroke, MSCs transplantation maintained BBB integrity through inhibiting aquaporin-4 (AQP4) upregulation and attenuating the upward trend of MMP9." (PMID 32613467, 2020). "We further examined AQP4 and eNOS expression, MMP-9 enzyme activity, and possible signaling pathways for the role of NBP after ischemic stroke." (PMID 33510620, 2020). "Studies on AQP-4 knockout mice (AQP4-KO) have reported considerable protection from brain edema induced by acute water intoxication and ischemic stroke, identifying AQP4 as a potential target for therapeutic interventions." (PMID 31220136, 2019). "On the other hand, hemorrhagic transformation is more common in reperfusion models and human large ischemic strokes, where high pressure blood reflow permeates through damaged BBB, and in these conditions, AQP4 inhibition would aggravate the vasogenic oedema." (PMID 29295526, 2017). "Data on AQP expression in cerebral edema, particularly AQP1 and AQP4, which are expressed in the CNS and participate in water transport across the BBB, come from some recent studies of large ischemic strokes." (PMID 21119879, 2010).